CXCR2 (C-X-C motif chemokine receptor 2)
Diseases named in the same sentence as CXCR2 in open-access papers (continued):
Sharing a sentence is not in itself a finding about the gene and the disease.
infection (continued). "A possible explanation is that Il22−/− showed a decrease in Cxcr2 expression after the peripheral infection had established (day 4 p.i.), and Il22−/− were also defective in brain Cxcl1 and Cxcl5 expression." (PMID 22952908, 2012). "In contrast, the chemokines CXCL1 and CXCL2, by binding to CXCR2, promote rapid release of neutrophils from the bone marrow, thereby elevating blood neutrophil counts during infection or during G-CSF-induced neutrophil mobilization." (PMID 21738479, 2011). "CXCR2 is the main receptor involved in neutrophil chemotaxis, leading to cell migration into the brain during injury, infection or disease." (PMID 21592385, 2011). "Even with past infection of H. pylori, it still may trigger CXCR2 signaling to induce cellular senescence through upregulating the related cytokines like NFKB1." (PMID 40051725, 2025). "CXCR2 expression levels in the KO neonates were significantly higher during infection." (PMID 40977737, 2025). "The CXCR2 signalling axis has proven to be crucial in several models of bacterial infection; however, previous observations have shown that a remarkably small number of neutrophils are recruited to sites of S. aureus biofilm-mediated infection." (PMID 38567642, 2024). "Thus, CXCR2 appears finely tuned to efficiently recruit effector cells and mediate control of S. aureus biofilm-mediated infection." (PMID 38567642, 2024). "In this study, the Cxcr2 gene was upregulated 7.54-fold at acute infection stages." (PMID 38229193, 2024). "Therefore, although these four chemokines all bind to CXCR2, they clearly demonstrate the complexity of different temporal and spatial expression profiles over the course of infection." (PMID 38352492, 2024). "The overarching goal of this study is to determine if S. aureus immunomodulation could be combated with therapeutic modification of CXCR2 activity, as this may lead to the identification of a novel therapeutic strategy to combat biofilm-mediated infections." (PMID 38567642, 2024). "Furthermore, we identified 1959 commonly expressed DEmRNAs, including IL27, Nos2, and Cxcr2, across two infection stages." (PMID 38229193, 2024). "Moreover, we found that the expression of PSGL-1 and CXCR2 was significantly increased at 6 h post-infection in the wound skin of Lanata-treated mice." (PMID 39877391, 2024). "Therefore, to assess the role of CXCL1, CXCL2, CXCL3, and CXCL5 in neutrophil trafficking during infection with C. violaceum, we used a CXCR2 inhibitor." (PMID 38352492, 2024). "We hypothesized that Lcn2 treatment would lead to reduced bacterial burdens during our implant model of S. aureus infection while CXCR2 antagonism would inhibit neutrophil recruitment and therefore increase infection severity." (PMID 38567642, 2024). "Future studies on the role of CXCR2-targeting virulence factors (i.e. ɣ-hemolysin AB, LukED, Staphopain A) during S. aureus biofilm-mediated infection may shed light on their contribution to thwarting neutrophil function via CXCR2 modulation." (PMID 38567642, 2024). "Interestingly, our results demonstrated that interaction scores of some paired ligands and receptors (e.g., ANXA1_FPR1, CD74_APP, CD74_COPA, CXCL1_CXCR1, CXCL2_CXCR2, and HLA-F_LILRB2) were significantly increased after infection." (PMID 37087411, 2023). "IL-8 attracts B lymphocytes to the site of infection, and migratory B lymphocytes are probably enriched with the CXCR2-expressing EBV-infected B cells and antigen-stimulated B cells, since we also observed an enhanced migratory response of the PMA-stimulated PBL." (PMID 36992360, 2023). "CXCL8, released by endothelial cells, and CXCR2 also play a key role in neutrophil attraction in sepsis, a potentially life-threatening condition characterized by an extreme response of the body to infection resulting in injury to its own tissues." (PMID 36725964, 2023). "The expression level of CXCR2 is tightly regulated during infection and inflammation." (PMID 35305619, 2022).
infection (continued). "Infection led to robust induction of chemokine and interleukin genes, including Il1b, Il6, Ccl2, Ccl3, Ccl4, Ccl7, Cxcl1, Cxcl2, Cxcl5, Cxcl9, and Cxcl10, and related receptor genes, including Ccr1, Ccr4, Ccr5, Ccr5, Ccr7, Cxcr2, Cxcr5, Il1r2, and Il1rn." (PMID 35487885, 2022). "CXCR2 function during infection strongly depends on the expressing cell type." (PMID 36451225, 2022). "The CXCR2 antagonist MK-7123 improved lung function in patients with moderate to severe COPD, but long-term treatment was associated with a reduction in circulating neutrophils and a slightly increased rate of infections." (PMID 35039631, 2022). "During these processes, the CXCLs-CXCR2 axis is a crucial biological pathway that might be key for understanding liver injury during life-threatening infection." (PMID 36451225, 2022). "In addition, CXCL1, CXCL2, and CXCL5 suppress excess CXCL13 expression in macrophages via the CXCR2 axis during the early infection stage." (PMID 34868067, 2021). "The CXCR2 blockade infection model further supported this notion." (PMID 34868067, 2021). "We also show that the absence of Cxcr2 not only leads to susceptibility to infection but also leads to reproductive defects due to major impairment of pituitary function controlling the production of pituitary hormones." (PMID 32041848, 2020). "Cxcr2 regulates wound healing, angiogenesis, multiple sclerosis, Alzheimer’s disease, atherosclerosis, respiratory diseases, resistance to infections, and is involved in cancer." (PMID 32041848, 2020). "Firstly, granulocytes from Tacrolimus pre-treated mice were less efficient in phagocytizing E. coli; secondly, they produced less MPO upon stimulation with E. coli; lastly, the chemokine receptor CXCR2 was markedly decreased in circulating granulocytes in the early hours of infections." (PMID 30643171, 2019). "The immunomodulatory protein vCXCL-1, a viral chemokine functioning primarily through the CXCR2 chemokine receptor, is hypothesized to attract CXCR2+ neutrophils to infection sites, aiding viral dissemination." (PMID 31239384, 2019). "These striking differences in fungal burdens were recently found to be due to candidalysin-dependent induction of IL-1β and CXCL1 secretion from CARD9+ microglial cells, which function to recruit CXCR2-expressing neutrophils to the brain to control the infection and hence reduce fungal burdens." (PMID 31401652, 2019). "CXCR2 is a chemokine receptor expressed on endothelial cells, oligodendrocytes, and various immune cells and is essential for neutrophil recruitment at tissue injury- or infection-induced inflammation sites." (PMID 26738635, 2016). "Phenotypic activation included up-regulation of CD11b, and down-modulation of CD62L, CD88 (via interaction with C5a), and CXCR2, all of which are consistent with the activation state of neutrophils and monocytes that have encountered a pathogen and are primed to combat an infection." (PMID 27812183, 2016). "In conclusion, these results suggest that due to elevated CXCR2 expression phagocytes and especially neutrophils are more rapidly recruited to the site of infection, where they are able to phagocytose more efficiently thanks to an increased expression of Dectin-1." (PMID 27078879, 2016). "Reduced peripheral MF in Aid-/- and Fcrg-/- mice were associated with increased lesion size and enhanced granulocyte infiltration at late timepoints post-infection, which could be reproduced by CXCR2 blockade." (PMID 25806513, 2015). "As CXCR2-driven neutrophil recruitment has been reported to contribute to protection against the helminth Strongyloides stercoralis, we first enumerated intestinal lesions and luminal parasites at day 14 post Hpb challenge infection." (PMID 25806513, 2015). "In addition, selective blockage of CXCR2 in vivo inhibited the increased neutrophil transmigration to the site of infection in fenofibrate-treated mice." (PMID 24755316, 2014).
infection (continued). "In contrast, CXCR2 expression was decreased at 24 and 48 h post-infection." (PMID 24613851, 2014). "Finally, blockage of CXCR2 abolished enhanced influx of neutrophils to the site of infection and subsequently diminished the survival of fibrate-treated mice." (PMID 24755316, 2014). "Furthermore, CXCR2 is predominantly responsible for neutrophil recruitment to the site of infection whereas, the CX3CR1 receptor regulates infiltration of peripheral macrophages and, plays important role in immune surveillance." (PMID 23626859, 2013). "CXCR2 neutralization also reduces circulating levels of neutrophils within uninfected mice (data not shown), suggesting that CXCR2 ligands contribute to both normal neutrophil homeostasis and emergency release following infection with a neurotropic virus." (PMID 19893623, 2009). "Furthermore, antagonization of CXCR2 led to the formation of thick fibrotic barriers at the biofilm-host tissue interface, similar to what has been observed previously in MyD88 knock-out mouse infections." (PMID 38567642, 2024). "Therefore, targeting CXCR2 to inhibit neutrophil infiltration and activation, thereby protecting liver resident non-immune cells, raises a potential therapeutic target to support the host response to infection, reducing hepatotoxicity." (PMID 36451225, 2022). "However, CXCR2 is involved cell-type specifically with multiple immunological and metabolic processes rendering one-target and one-time fits-all strategies unlikely to be a reliable solution to treat liver injuries, particularly during infection." (PMID 36451225, 2022). "In the same study also impaired chemotactic recruitment of neutrophils to L3 within diffusion chambers in CXCR2-deficent mice resulted in impaired larval killing in naive and immune mice, thus providing indirect evidence for neutrophil function during primary and secondary infection in vivo." (PMID 34475874, 2021). "To further investigate whether the impaired neutrophil migration is due a deficient neutrophil activation status during infection, we accessed the expression of the markers CD11b, CD62L and CXCR2 in circulating neutrophils after A. fumigatus infection using flow cytometry." (PMID 32701055, 2020). "Indeed, the CXCR2 expression levels were significantly upregulated 2 days after infection." (PMID 29445104, 2018). "ScpA also cleaves the neutrophil chemotaxis receptor CXCR2, blocking neutrophil recruitment, and exhibits activity against the extracellular matrix protein collagen, whose degradation could promote host damage during infection." (PMID 27747296, 2016). "CXCL1 specifically targets neutrophils through the receptor CXCR2 promoting chemotaxis and activation of neutrophils but despite the initial significant increase of CXCL1 expression in Fas- and FasL-deficient mice at 3rd day of ECTV infection, later during infection we observed an opposite effect." (PMID 25873756, 2015). "At times early following infection, multiple transcripts encoding proinflammatory molecules were increased, including IL8 (8196-fold), IL1B (1559-fold), oncostatin M (OSM, 799-fold), CCR1 (588-fold), CXCR1 (625-fold), CXCR2 (596-fold), CCL4 (514-fold), and CCL3 (658-fold)." (PMID 25719526, 2015). "Similarly, the Cxcr2 antagonist SB225002 caused no loss or decrease in anti-nitrotyrosine signal accumulation after Mm infection." (PMID 24967596, 2014). "Interestingly, IL-8 binding to CXCR2 triggers the rise of intracellular calcium from intracellular stores, which may in turn contribute to infection." (PMID 24812617, 2014). "The dissemination of CXCR2 and CXCL1 in murine pulmonary endothelial and epithelial cells following infection with K. pneumoniae was analyzed by transmission electron microscopy." (PMID 40413164, 2025). "The chemotaxis of neutrophils towards the infection site depends on the binding of CXCL-8 to the G protein-coupled cell surface receptors CXCR1 and CXCR2 expressed by infected epithelial cells." (PMID 40475997, 2025).
infection (continued). "IL-8 and its receptor, C-X-C chemokine receptor type 2 (CXCR2), play a central role in inflammation by mediating neutrophil recruitment and activation at sites of tissue injury or infection." (PMID 41514867, 2025). "Macrophages express CXCR-2, which facilitates the release of chemokines such as CXCL-1 and CXCL-2 to recruit T cells to sites of inflammation or infection." (PMID 40585992, 2025). "Blood samples were drawn in RNA preservative (Tempus) and whole blood RNA was analyzed by droplet digital PCR (ddPCR) for RNA transcripts related to neutrophil response to infection by bacterial (DEFA1; ALPL, IL8RB/CXCR2), and viral (IFI27, RSAD2) pathogens." (PMID 41385588, 2025). "The observed infiltration of immune cells after infection with swH1N1 agrees with the upregulation of chemotactic factors (AMCF-II, CXCL8/IL8, CXCL2, CXCL10, and CCL20) and their receptors (CCR1 and CXCR2) at the transcriptional level." (PMID 39247193, 2024). "MRNA and protein expression of CXCR2, PSGL-1, and MPO in neutrophils in the peripheral blood in both MRSA + Lanata and MRSA groups first increased post-infection, followed by a decrease." (PMID 39877391, 2024). "In our study, we found that CXCR2 expression in neutrophils in peripheral blood in the Lanata group followed the same trend as PSGL-1 (i.e., increase in the acute stage of infection as compared with the MRSA group)." (PMID 39877391, 2024). "Interleukin 8 receptor beta (CXCR2) plays a critical role in regulating neutrophil migration and recruitment to sites of infection or injury." (PMID 39337409, 2024). "Using RT-qPCR, flow cytometry, and ELISA, we found that the mRNA and protein levels of CXCR2, PSGL-1, and MPO in the neutrophils of the MRSA + Lanata group increased significantly at 6 h post-infection and were lower than those in the MRSA group after 12 h." (PMID 39877391, 2024). "We found that, similar to that observed with expression of PSGL-1 and CXCR2, MPO expression in the neutrophils of Lanata-treated mice increased at 4 h and 6 h post-infection, reaching the peak at 6 h." (PMID 39877391, 2024). "High CXCL3 levels have been detected in mouse brain tissue after infection, and CXCL3 interacts with CXCR2 (the receptor) to produce a range of biological effects." (PMID 37445610, 2023). "CXCR2 is the receptor for CXCL1, which is produced in the respiratory tract during infection with B. pertussis in response to IL-17." (PMID 33976385, 2021). "Multiple factors contribute to neutrophil recruitment from the circulation to the site of infection, including proinflammatory cytokines (such as IL-1α, IL-1β, TNF-α, and IL-6) and Cxcr2 chemokines (such as Cxcl1, Cxcl2, Cxcl5, and Cxcl8)." (PMID 34011393, 2021). "Mechanistically, chronic ethanol consumption impairs the normal neutrophil migration to the site of infection via release of high levels of circulating chemokine CXCL1 after infection, followed by downregulation of its receptor 2 (CXCR2)." (PMID 32701055, 2020). "Our results show that CXCL8 mediates productive infection of HIV-1 in MDM and microglia via receptors CXCR1 and CXCR2." (PMID 24662979, 2014). "Similarly, UMAP plots of BALF showed a clear shift in the CXCR4+ CXCR2+, and CCR5+ populations during infection." (PMID 40475786, 2025). "We observed dysregulated neutrophil phenotypes late in infection of A/J mice compared to B6 mice including reduced maturity, NET release, and CXCR2 expression, and increased respiratory burst capacity, immunosuppressive-like marker expression, costimulatory marker expression, and degranulation." (PMID 39823516, 2025). "Surprisingly, there was no significant change in the CXCR2 expression observed in splenic mononuclear cells from WT pups during infection." (PMID 40977737, 2025). "In contrast, CXCR2 expression was upregulated significantly in KO neonates during infection but failed to increase in WT neonates." (PMID 40977737, 2025).
infection (continued). "Additionally, CXCR2 LOF mice displayed progressive mortality, with a 46% mortality rate by day 2 post-infection, compared to 23% in control mice." (PMID 41451234, 2025). "Overall, our findings suggest that during infection in the absence of IL-27 signaling, a differential expression of CXCR2 and CXCL2 promotes increased migration of mononuclear cells consistent with improved bacterial clearance and tissue homeostasis." (PMID 40977737, 2025). "This suggests that mononuclear cells from IL-27Ra KO mice are not inherently programmed to express CXCR2 at higher levels than WT, and instead, respond to the environment during infection to modulate their receptor expression level." (PMID 40977737, 2025). "Similarly, the expression of CXCR2, PSGL-1, and MPO in neutrophils in the air pouch in the MRSA + Lanata group increased significantly at 6 h post-infection and were lower than those in the MRSA group at 12 h." (PMID 39877391, 2024). "On the contrary, infection reduced the percentage of neutrophils expressing CD62L and CXCR2." (PMID 39156897, 2024). "There was no change in the expression of the receptors IL1-R1 and CXCR2 within the site of infection or on the circulating leukocytes." (PMID 39509414, 2024). "Remarkably little is known of the role CXCR2 plays during S. aureus infection, and the role of CXCR2 during biofilm-mediated infection has not been investigated." (PMID 38567642, 2024). "In this online database, the CXCR1 expression was also scarce and did not change during the time course of the infection, while the CXCR2 expression was expressed basally and further induced by the EBV infection." (PMID 36992360, 2023). "The result showed that infection of PR8 significantly reduced the body weights of virus-infected mice compared to the control mice, while treatment with phillyrin-only, CXCR2 antagonist SB225002-only, phillyrin and SB225002 synergistically significantly alleviated this loss." (PMID 37957672, 2023). "When the dLN and spleen were examined at PID 3, flow cytometric analysis demonstrated that both wt and delNSs SFTSV infection resulted in significant increases of CXCR2+, Ly6G+, and CD11b+ neutrophils in the spleen but not in the dLN." (PMID 35529317, 2022). "Cxcr2 (but not Cxcr1) mediates infection-induced neutrophil mobilization from the caudal hematopoietic tissue (CHT) to infectious foci." (PMID 32161595, 2020). "Interestingly, another CXCR2 agonist and neutrophil chemotactic mediator, CXCL2 were increased at 24 hr of infection in BAL fluid of ethanol-treated mice compared to control mice." (PMID 32701055, 2020). "Our results have demonstrated that when exposed to common infections found in animal facilities, Cxcr2 KO mice, but not WT mice, exhibit reproductive defects." (PMID 32041848, 2020). "As shown by the regression models, septic shock status predicts CXCR2 surface level over time while infection status does not." (PMID 33424860, 2020). "Teleost CXCR1 and CXCR2 are conserved receptors for interleukin-8 (IL-8, also termed CXCL8) and are important for the regulation of neutrophil recruitment and migration to sites of infection and injury." (PMID 30837998, 2019). "CXCR1, and mainly CXCR2 expression, on neutrophils grants an additional form of chemotaxis away from the bone marrow via their respective ligands, CXCL1 and CXCL2, which are produced by macrophages and mast cells at the site of infection." (PMID 30791481, 2019). "In these animals, CXCR2 is not lost from the surface of neutrophils and recruitment of this cells is sufficient to control infection,–i.e., there is no failure of neutrophils to migrate." (PMID 26147469, 2015). "The observed down-regulation of chemokine (CCL4) and chemokine receptors (CCR1, CXCR2, CX3CR1, C5aR) could impair the proper inflammatory response at the site of infection as they play a crucial role in immune cell trafficking." (PMID 23626859, 2013).